BMP7 (bone morphogenetic protein 7)
Diseases named in the same sentence as BMP7 in open-access papers (continued):
Sharing a sentence is not in itself a finding about the gene and the disease.
breast carcinoma (continued). "More precisely, the effects of BMP2 and BMP7 treatments on transcription in MCF-7 and MDA-MB-468 breast cancer cell lines, respectively, have been analyzed using cDNA microarrays of limited content (from several hundreds to 14, 500 gene probes)." (PMID 22118688, 2011). "In this study, we have therefore set up an experimental procedure to identify potential BMP target genes in breast cancer by studying the effects of two BMP ligands, BMP4 and BMP7, on genome-wide gene expression." (PMID 22118688, 2011). "A cross-talk between Bmp7 and Tgf-β signaling in the regulation of EMT in breast cancer is proposed, and Bmp7 was identified as a potential key molecule in therapy for metastatic bone disease." (PMID 19424481, 2008). "In breast cancer, TGF-β2 and BMP7 derived from NG2+/Nestin+ MSCs maintains dormancy." (PMID 41091336, 2025). "The osteotropic behavior of tumor cells is driven by bone-specific metastatic signaling molecules such as matrix metalloproteinase-9 (MMP-9) and bone morphogenetic protein-7 (BMP-7), which are highly expressed in prostate and breast cancers and promote EMT and bone invasion." (PMID 34440874, 2021). "In order to confirm these effects are not specific to 344SQR cell line, we tested if BMP7 knockdown in 4T1 mouse mammary carcinoma model promote sensitivity to anti-PD1 therapy." (PMID 32973129, 2020). "Interestingly, BMP7, an antagonist to EMT, which inhibits breast cancer metastasis, was a top gene that was downregulated in metastatic tumors." (PMID 31881983, 2019). "Thus, we show that BMP7 inhibits telomere maintenance by a mechanism involving BMPRII receptor and Smad3 signaling to suppress hTERT gene expression in breast cancer cells." (PMID 27696331, 2017). "Consistently, silencing the hTERT gene induces breast cancer cell death without potentiating the effect of BMP7 on cancer cell death." (PMID 27696331, 2017). "To this end, we selected breast cancer cell lines with low endogenous expression of BMP4 (HCC1419, SK-BR-3), BMP7 (MDA-MB-231, T-47D) or both (HCC1954, MDA-MB-361, ZR-75-30) and treated them with the corresponding BMP ligand (rhBMP4 or rhBMP7) and vehicle controls." (PMID 22118688, 2011). "Moreover, whereas treatment with TGFβ1 had little impact on ID2 expression in either mouse mammary carcinoma or human breast cancer cells, BMP7 treatment resulted in a > 50-fold increase in ID2 mRNA levels and this level of expression was sustained for at least 5 days following BMP7 withdrawal." (PMID 30642388, 2019). "Bone morphogenetic protein 7 (BMP7), a TGF-β-induced EMT antagonist, was a positive regulator of mesenchymal–epithelial transition (MET, the reverse of EMT) and was significantly decreased in mice of chronic renal injury, which was demonstrated in prostate and breast cancer cells too." (PMID 29254283, 2017). "We found BMP7 is upregulated in triple negative (ER−PR−HER2−) and Her2+ breast cancer, but not in luminal cancer." (PMID 38708713, 2024). "Of note, BMP4 and BMP7 did not alter the RFP content of the mammosphere cells, and these 3D cultures appeared much closer to controls, which agrees with the previously established pro‐MET action of the BMPs on breast cancer cells." (PMID 35348275, 2022). "Sostdc1 blocks the Smad phosphorylation induced by BMP7 without diminishing BMP2 or Wnt3a-induced signalling in breast cancer cells, indicating that Sostdc1 is a clinically important extracellular regulator of various signalling pathways in breast cancer." (PMID 36338475, 2022). "To investigate whether or not the observed telomerase inhibition induced by BMP7, mediated by BMPRII receptor, is limited to the MCF-7 breast cancer cell line, we exploited another breast cancer cell line—PMC42 cells." (PMID 27696331, 2017).
prostate carcinoma (54 papers, 2008 to 2023). A carcinoma that arises from epithelial cells of the prostate gland. "Loss of BMP7 in glioblastoma, breast, and prostate cancers, therefore, predisposes to enhanced EMT and acquisition of invasive/metastatic traits suggesting a protective role for BMP7 in cancer progression." (PMID 29799477, 2018). "BMP7 deficiency accelerates tumorigenesis and negatively correlates with patient survival in prostate cancer." (PMID 29799477, 2018). "BMP-7 has also been implicated to control prostate cancer growth and spread, however, its potential relationship to WISP1 remains to be clarified." (PMID 23977121, 2013). "However, BMP-7 expression in metastatic prostate cancer tissues is associated with shorter patient survival, suggesting a context-dependent contribution of BMPs in prostate cancer." (PMID 35693928, 2022). "Morrissey and colleagues found that BMP7 is expressed at higher levels in prostate cancer‐related bone and soft tissue metastasis in comparison to primary prostate cancer suggesting BMP7 signalling is associated with tumour metastasis and cancer progression." (PMID 37688374, 2023). "Initial reports highlighted BMP7’s ability to curtail tumor growth by upregulating CDKN1A in prostate cancers." (PMID 38049682, 2023). "BMP7 exercises control over epithelial homeostasis within the human prostate, safeguarding the epithelial phenotype and impeding bone metastases of prostate cancer in vivo." (PMID 38049682, 2023). "We have also reported that BMP-7 inhibits the proliferation of prostate cancer cells in cell culture and a xenograft model." (PMID 35693928, 2022). "BMP-7 also inhibits prostate cancer cell proliferation by inducing p21 and suppressing CDK2 activity." (PMID 35693928, 2022). "An in vivo study showed that withdrawal of BMP7 significantly abrogated the suppressive effect of osteoblasts and induced metastatic growth of stem-like prostate cancer cells in the bone." (PMID 36307871, 2022). "Of note, BMP-7 is also abundant in the bone microenvironment, potentially contributing to the bone metastatic niche of prostate cancer, as it was shown that prostate cancer cells undergo EMT when experimentally inoculated into mouse bone." (PMID 34831167, 2021). "High BMP7, NODAL, and Snail gene expression in metastatic prostate cancer tissues is associated with shorter survival in patients with prostate cancers and offers potential therapeutic targets among the EMT-related genes downregulated by BBR." (PMID 34885950, 2021). "Further emphasizing the relationship between tumor dedifferentiation and EMT, the hedgehog and bone morphogenic protein (BMP)-7 developmental signaling pathways are reactivated in aggressive prostate cancer and can induce EMT." (PMID 34831167, 2021). "Loss of BMP7 in glioblastoma, breast and prostate cancers, predisposes to enhanced EMT and acquisition of invasive/metastatic traits suggesting a protective role for BMP7 in cancer progression." (PMID 33823905, 2021). "SPARC, also known as osteonectin, was shown to regulate tumor dormancy of prostate cancer cells by promoting the expression of BMP7 in BM stromal cells." (PMID 33987095, 2021). "Investigations on prostate cancer revealed that, BMP7 (bone morphogenetic protein 7) regulated dormancy of prostate cancer cells through affecting cancer stem cell population." (PMID 33816262, 2021). "In two additional studies, osteoblast expression of TGF-beta and Gas6, as well as BMP7, maintained bone metastatic prostate cancer cells in a dormant state, whereas reduction of those factors promoted prostate cancer cell growth." (PMID 33572757, 2021). "This in turn promoted BMP7 expression in BM stromal cells leading to dormancy of prostate cancer cells." (PMID 33987095, 2021). "BMP7 was highly expressed in metastatic bone lesions of prostate cancer, and expression was related to osteoblastic metastasis." (PMID 34437475, 2021).
prostate carcinoma (continued). "Other factors, such as bone morphogenetic protein 7 (BMP7), can induce dormancy of prostate cancer cells." (PMID 34063848, 2021). "One of the first factors that was identified in cellular dormancy was BMP-7, which induces a reversible proliferation arrest in bone metastatic prostate cancer cells, through p21, p38 and n-myc downstream-regulated gene (NRDG)-1." (PMID 32527062, 2020). "A further study done by Masuda and colleagues found a high expression level of BMP-7 in the normal prostate glandular tissues while BMP-7 expression was low during the development and progression of prostate cancer." (PMID 31137764, 2019). "Specifically, the expression of BMP-3 and BMP-5 was relatively higher whereas the expression of BMP-7 was comparatively lower in prostate cancer tissue than normal tissue." (PMID 31137764, 2019). "Within a bone metastatic model of prostate cancer, systemic treatment of BMP7 prevented the outgrowth of tumor cells and maintained a dormant phenotype." (PMID 29642534, 2018). "BMP7 is secreted from bone stromal cells and induces a quiescent phenotype in prostate cancer cells via the binding of BMPR2, of which the expression level is inversely correlated with bone metastasis recurrence." (PMID 29642534, 2018). "For instance, evidence was provided that BMP7 (bone morphogenetic protein 7), secreted by bone stromal cells, plays a key role in dormancy and recurrence of prostate cancer." (PMID 29197379, 2017). "BMP7 is also readily detectable in solid tumors including breast and prostate carcinomas, and involved in regulating tumor cell proliferation and transition." (PMID 27696331, 2017). "Increased expression of BMP7 was also identified in bone metastatic breast cancer and prostate cancer." (PMID 28455969, 2017). "BMP co-receptor repulsive guidance molecule b (RGMb) was upregulated in vascular endothelial cells after hepatocyte growth factor (HGF) stimulation, which was combined with BMP-7 to induce angiogenesis in breast and prostate cancers." (PMID 27661009, 2016). "Berberine, a natural alkaloid with important antitumor activities, has exerted inhibitory effects on the migratory and invasive abilities of highly metastatic prostate cancer cells by downregulating BMP-7." (PMID 27661009, 2016). "Down-regulated BMP7 expression was also determined in primary human prostate cancer tissue when compared with normal prostate luminal epithelium." (PMID 26546412, 2015). "From previous studies, DUSP4 and BMP7 are known to be methylated in gliomas and gastric- and prostate cancer, respectively." (PMID 25226156, 2014). "Some in vitro studies indicate that Bmp7 and other Bmp ligands are potent inhibitors of tumor growth and metastasis in prostatic cancer cell lines." (PMID 24731097, 2014). "Previously studies have shown that BMP-7 overexpression is indeed a prognostic indicator for accelerated metastasis formation in breast and prostate cancer." (PMID 25390068, 2014). "In the C4-2B prostatic cancer cells, BMP7 is able to promote cell survival by inhibiting stress-induced apoptosis in culture-free medium conditions via both the smad/survivin and c-jun NH2-terminal kinase pathway putatively through survivin overexpression." (PMID 24069261, 2013). "Increased expression of BMP-7 has been detected in prostate cancer to bone metastases, and high-level expression of BMP-7 is related to osteoblastic activity of the metastatic lesion." (PMID 20010941, 2010). "Whereas numerous studies have been conducted on the effects of BMP-7 on breast and prostate cancers, little has been reported on the effects of BMPs in general and BMP-7 in particular on lung and kidney cancer to date." (PMID 23675191, 2010). "Similarly, reduced secretion of BMP-7 by osteoblasts and MSCs resulted in enhanced prostate cancer cell proliferation in vitro and in vivo." (PMID 34831167, 2021).
prostate carcinoma (continued). "Furthermore, SPARC, a matrix-associated protein expressed and secreted by prostate cancer cells, induces dormancy of bone cells, a process sustained by SPARC-mediated activation of BMP7 secretion." (PMID 34135460, 2021). "Intriguingly, several years later an independent report showed that osteonectin activation in MSC-lineage cells promotes BMP-7, which could then lead to prostate cancer dormancy." (PMID 32527062, 2020). "Additionally, BMP7, produced from bone stromal cells, can induce dormancy in prostate cancer cells by activating p38 signaling." (PMID 32300189, 2020). "Bone morphogenetic protein 7 (BMP-7) secreted from BM stromal cells can inhibit proliferation of prostate cancer stem-like cells by activating p38 MAPK signaling and increases expression of N-myc downstream regulated gene 1 (NDRG1), a metastasis suppressor gene." (PMID 31817646, 2019). "Furthermore, in a study by Kobayashi and colleagues, reduction of osteoblast- and mesenchymal stromal cell-derived BMP7 led to increased PC3 prostate cancer cell growth both in-vitro and in-vivo." (PMID 29867053, 2018). "Notably, it was reported that BMP7-induced senescence of prostate cancer stem-like cells is reversible; withdrawal of BMP7 treatment restarted growth of these cells in bone." (PMID 26546412, 2015). "Accumulating evidence reveals that high-level expression of BMP-7 correlates with increased invasion and metastasis in various malignancies, including breast cancer, colorectal cancer, prostate cancer, esophageal cancer, gastric cancer, lung cancer, liver cancer, and melanoma." (PMID 25390068, 2014). "Of note, BMPRII is frequently lost from prostate cancer epithelium, as is BMP7." (PMID 23967299, 2013). "In addition, bone morphogenetic protein 7 (BMP7) secreted by osteoblasts induced the dormancy of PC-3 prostate cancer cells by upregulating the mRNA expression of N-myc downstream-regulated gene 1 (NDRG1), a metastasis suppressor gene, via activating p38 and p21." (PMID 36307871, 2022). "Additionally, Endoglin, a transforming growth factor beta superfamily auxiliary receptor, was shown to inhibit prostate cancer motility via activation of the Alk2/Smad1 pathway, and BMP7 inhibition of epithelial-to-mesenchymal transition was lost when Alk2 were knocked down in a melanoma cell line." (PMID 22457812, 2012). "The osteogenic protein BMP-7 and endopeptidase MMP-9 are upregulated in both breast and prostate cancer bone metastases." (PMID 34440874, 2021). "This idea is supported by two studies, reporting that BMP7 and SPARC, respectively, maintain prostate cancer cells in dormancy by inducing senescence." (PMID 34135460, 2021). "For example, HOXC6 directly regulates gene expression of Bone morphogenetic protein 7 (BMP7), Fibroblast growth factor receptor 2 (FGF2), and Platelet-derived growth factor receptor (PDGFR) in prostate cancer." (PMID 30993034, 2019). "Recently, indolent prostate cancer cells have been reported to secrete SPARC, which can induce BMP7 secretion by bone marrow stromal cells, further supporting the role of BMP7 in inducing prostate cancer stem cell senescence." (PMID 27782035, 2016). "For example, HOXC6, a homeobox transcription factor, regulates the expression of genes including BMP7, FGFR2, IGFP3 and PDGFRA to influence oncogenic activities in prostate cancer." (PMID 24009521, 2013). "This technique has been previously used in our laboratory to provide accurate and quantitative methylation profiles of multiple CpGs in the Bone morphogenetic protein 7 (BMP7) and HOXD3 genes in prostate cancer samples." (PMID 23342273, 2012). "BMP7 is an antagonist of the TGF-β pathway and can inhibit osteolytic metastasis attributable to prostate cancer." (PMID 20696077, 2010). "BMP-7, another member of the BMP family, has been reported to be a potent inhibitor of prostate cancer metastasis also acting through E-cadherin induction." (PMID 20537156, 2010).
prostate carcinoma (continued). "Similarly, BMP-2 and BMP-7 were reported to promote the characteristic morphologic conversion of EMT in gastric and prostate cancer cells." (PMID 27661009, 2016). "A previous study revealed that BMP7 may inhibit TGF-β-induced EMT and bone metastasis in both breast and prostate cancer by decreasing αvβ3 integrin expression." (PMID 25849225, 2015). "Several ways to induce EMT in prostate cancer cells have been described, including overexpression of CAV1 and ID1 or MMP14 in LNCaP cells, EGF treatment of DU145 cells, depletion of PDEF or BMP7 treatment of PC3 cells." (PMID 18852876, 2008). "However, not all BMP ligands assume tumor-promoting roles in prostate cancer; BMP7, in particular, stands as an exception." (PMID 38049682, 2023). "Furthermore, BMP7 induces reversible senescence and growth arrest of cancer stem cells (CSCs) both in vitro and in vivo, achieved by upregulating NDRG1 through the p38 pathway in prostate cancer." (PMID 38049682, 2023). "Further validation of candidate genes on a separate cohort of low and high grade prostate cancers by quantitative MethyLight analysis has allowed us to confirm DNA hypermethylation of HOXD3 and BMP7, two genes that may play a role in the development of high grade tumours." (PMID 19283074, 2009). "In addition, berberine inhibited prostate cancer cell invasion and migration by downregulating several EMT-related genes, such as platelet-derived growth factor receptor-beta (PDGFRB), collagen, type I, alpha 2 (COL1A2), and bone morphogenetic protein 7 (BMP7)." (PMID 35889396, 2022). "Dormant prostate cancer cells, but not proliferative cells, secreted SPARC, a factor which stimulated BMP7 expression from bone marrow stromal cells, contributing to the maintenance of dormant phenotype." (PMID 33816262, 2021).